CRP (C-reactive protein)
Diseases named in the same sentence as CRP in open-access papers (continued):
Sharing a sentence is not in itself a finding about the gene and the disease.
bacteremia (continued). "Three (5%) patients who suffered from chronic inflammatory disease (1 patient had well-controlled ulcerative colitis, 1 had dermatitis of the lower legs, and 1 had elevated C-reactive protein after bacterial sepsis) reported that it is a contraindication for vaccination." (PMID 34960141, 2021). "The type of infection focus was significantly associated with clinical parameters: while patients with intravascular device-related bacteremia were more likely to experience fever but had lower CRP levels, patients with bone and joint-focused SAB presented with less fever but higher CRP levels." (PMID 33800644, 2021). "We found a wide spread of CRP levels between various causes of bacteremia, with Gram-negative causes of bacteremia (e.g., Salmonella) having significantly lower CRP levels compared to Gram-positive causes of bacteremia (p = 0.02)." (PMID 33647009, 2021). "Other methods to diagnose bacteremia in the clinic include the measurement of white blood cells, the neutrophil-to-monocyte ratio, or the level of inflammatory markers such as C-reactive protein (CRP), procalcitonin, and interleukin-6." (PMID 33535571, 2021). "The NLR was better value in predicting bacteremia than routine parameters like CRP." (PMID 33109144, 2020). "However, bacteremia continued to increase in H38R CRP-treated mice, like in untreated mice, and mice died once bacteremia was >108 CFU/ml." (PMID 32903624, 2020). "Indeed, biomarkers such as CRP, ferritin, and procalcitonin are frequently elevated in generalized inflammatory conditions including bacterial sepsis." (PMID 33335786, 2020). "Using CRP to properly manage children with fever may help identify true bacteremia and reduce unnecessary antibiotic therapy." (PMID 32429293, 2020). "Age ≤90 days, higher DNI and CRP values may help predict bacteremia of febrile infants younger than 6 months with UTI." (PMID 32161316, 2020). "In children with bacteremia, the inflammation-associated cytokines produced primarily by WBC at inflammatory sites may further cause the elevation of CRP level and induce reactive thrombocytosis." (PMID 32429293, 2020). "The protective effect of CRP is due to reduction in bacteremia." (PMID 30863393, 2019). "Indwelling urinary catheter and increased C-reactive protein levels were risk factors of septic shock in UTI patients with or without bacteremia." (PMID 31867338, 2019). "In the present study, bacteremia was defined as culture-positive bacterial infection in serial results of blood culture at febrile event, and finally, PCT had better diagnostic accuracy for bacteremia than CRP." (PMID 31821331, 2019). "High NLR combined with lymphocytopenia may be a better predictor of bacteremia than other routinely used parameters in the emergency department, such as CRP and the leucocyte count." (PMID 31648506, 2019). "Eleven patients (55% S. aureus) had negative outcome (secondary bacteremia or death) and they demonstrated sustained C-reactive protein elevation, neutrophilia, lymphocytopenia, and loss of mHLA-DR." (PMID 29466395, 2018). "In the present study, we found that CRP at a cut-off of 20 mg/mL had the highest sensitivity (88%) for bacterial sepsis as defined by Sepsis-3 criteria, whereas both PCT at a cut-off 10.0 ng/mL and lactate at a cut-off of 4.0 mmol/L showed high specificity (97%)." (PMID 28727802, 2017). "In situations involving HD patients suspected of having bacteremia, although the body temperature, heart rate, history of antibiotic use and CRP are evaluated as a rule in general, the addition of ALP measurement may further support making clinical decisions." (PMID 28081211, 2017). "In our case, the initial CRP increased 20 times following bacteremia development." (PMID 27738536, 2016). "Raised CRP levels are found in 50-90% of neonates from six hours of onset of bacteremia." (PMID 26150837, 2015).
bacteremia (continued). "In the presence of major clinical risk factors, recurrent CRP elevation, persistent bacteremia and nonspecific symptoms, a localized focus of infection should be suspected." (PMID 26239708, 2015). "However, CRP was a better marker than eosinophil count for the diagnosis of bacteremia in critically ill patients." (PMID 24903083, 2014). "This dissemination may induce a bacteremia or endotoxemia that is characterized by increased serum levels of inflammatory mediators such as C-reactive protein (CRP), IL-6, and fibrinogen." (PMID 23497572, 2013). "In this study in mice, we determined whether blood culture, CRP, and cytokines are potential biomarkers for presence and outcome of S. aureus bacteremia." (PMID 23520553, 2013). "As CRP is not specific for S. aureus infection, elevated CRP levels will not indicate bacteremia caused by S. aureus only." (PMID 23520553, 2013). "Two studies specifically reported a relationship between bacteremia and CRP concentrations." (PMID 24286072, 2013). "CRP was adjusted for malaria and bacteremia; IL-6 was adjusted for bacteremia." (PMID 24339866, 2013). "C-reactive protein and elevated white blood cells had low predictive values for bacteremia, while elevated procalcitonin levels were correlated with positive blood culture findings, confirming its diagnostic value in general ICU settings and in particular clinical scenarios." (PMID 22351576, 2012). "sTREM-1, PCT, and CRP levels are of no use in determining new fever caused by bacteremia in ICU patients, but sTREM-1 levels reflect the prognosis of bacteremia." (PMID 22809118, 2012). "In addition, the systemic involvement in acute pyelonephritis causes fever and elevated acute phase reactants like C-reactive protein (CRP) and in about 30% of adults, pyelonephritis is accompanied by bacteremia." (PMID 22140570, 2011). "When episodes of bacteremia caused by Gram-positive and Gram-negative bacteria were compared, CRP and IL-6 blood level were found to be significantly higher in Gram-negative bacteremia." (PMID 20202204, 2010). "Although fever and high leucocyte and C-reactive protein levels may simply reflect the presence of systemic inflammatory response, procalcitonin is useful in differentiating bacterial sepsis from systemic inflammatory response in critically ill patients." (PMID 18454864, 2008). "We studied the association of clinical factors, CRP levels and changes of CRP documented prior to blood culture draws with the absence of bacteremia for hospitalized medical patients." (PMID 18957115, 2008). "In this study we analyzed the significance of serum levels of the proinflammatory cytokines IL-6 and IL-8 as well as C-reactive protein as predictors for severe bacterial infection or bacterial sepsis in children with fever and neutropenia during cancer chemotherapy." (PMID 18321393, 2008). "IL-8 levels decreased within 72 h considerably earlier than CRP in the absence of documented bacteremia, potentially informing antibiotic de-escalation, though its moderate specificity (77.3%) and lack of bacteremia cases in this cohort preclude standalone diagnostic use." (PMID 40647525, 2025). "However, the high levels of CRP—a reliable marker of systemic inflammation—detected in this animal 7–8 dpi suggest that a bacteremia spike may have occurred in the days between 2 and 7 dpi." (PMID 40766078, 2025). "Therefore, we believe that CRP levels could serve as a useful predictor of bacteremia in young febrile infants." (PMID 37679686, 2023). "Multivariable logistic regression revealed that higher levels of C-Reactive protein (CRP) (OR = 1.01) and the use of continuous veno-venous hemofiltration (CVVH) treatment (OR = 2.93) were independently associated with an elevated risk of developing bacteremia." (PMID 37768395, 2023).
bacteremia (continued). "Conversely, PCT with a 3 ng/L cut-off and CRP with a 130 mg/mL cut-off were moderately discriminative (p = 0.012 and p < 0.001, respectively), giving positive results for 76% and 68% of candidemia patients, respectively, compared to 56% and 38% of bacteremia patients, respectively." (PMID 35330311, 2022). "The present single-center, prospective, observational pilot study demonstrated the robust increase of serum hepcidin in patients with bacteremia caused by different microbial agents and its decline in response to adequate antibiotic treatment, mostly in correlation with CRP but not ferritin." (PMID 35741214, 2022). "Duration of hospital stay after FDG-PET/CT, ICU admission, bacteremia caused by Gram-negative or multiple bacteria, leukocyte count, CRP, platelets, detecting any focus of infection on FDG-PET/CT, and having a cardiovascular or musculoskeletal focus of infection were positively associated with BLR." (PMID 33106925, 2021). "CRP and PCT are also used as surrogate markers of pneumococcal infection in studies evaluating the effectiveness of pneumococcal conjugate vaccines (PCVs); confirming the association between routinely available biomarkers and bacteremia would further support their use as endpoints in PCV trials." (PMID 34746044, 2021). "However, clinical symptoms of the patients that were included in this review were relatively heterogeneous, ranging from asymptomatic courses to severe disease, which was mainly defined by fever, CRP levels and/or bacteremia, as well as the need for hospitalization and the severity of diarrhea." (PMID 34680768, 2021). "With multivariate linear regression, age was the strongest factor independently associated with BLR, followed by CRP, having a cardiovascular of musculoskeletal focus of infection, having bacteremia caused by Gram-negative bacteria, and blood glucose level before FDG-PET/CT." (PMID 33106925, 2021). "Bacteremia caused by Gram-negative bacteria, Staphylococcus aureus, or multiple bacteria, leukocyte count, CRP, detecting any focus of infection on FDG-PET/CT, and having a cardiovascular or musculoskeletal focus of infection were positively associated with SLR." (PMID 33106925, 2021). "Here we describe the diagnostic accuracy of the IMS to detect bacteremia and other bacterial infections in patients with AFI in a malaria endemic area in Burkina Faso, with reference to standard microbiological and clinical diagnostics, and compared to CRP and PCT." (PMID 33647009, 2021). "In addition, the clinicians should pay attention to high WBC counts, CRP levels and proportions of neutrophil band forms, development of bacteremia and mediastinitis which might imply a potential of mortality in patients with DM-DNI." (PMID 34683380, 2021). "In addition, patients with bacteremia had significantly higher median lactate level (3.3 vs. 2.6 mmol/L), C-reactive protein (CRP) level (16.5 vs. 15.3 mg/dL), and serum procalcitonin (PCT) concentration (21.3 vs. 5.2 ng/mL; p < 0.01, p = 0.02, and p < 0.01, respectively)." (PMID 32076046, 2020). "Multivariate logistic regression analysis demonstrated that neutropenia and PCT level, but not CRP level, were significantly associated with bacteremia [odd ratio (95% CI): 8.220 (4.645–14.549) for neutropenia (P < 0.001) and 1.048 (1.025–1.071) for PCT (P < 0.001)]." (PMID 31821331, 2019). "Interestingly, widely used parameters such as CRP or WBC showed low discriminatory capacity to differentiate between systemic inflammation based on infection or other causes or bacteremia and non-bacteremia in patients with SIRS." (PMID 24349403, 2013). "Taken the relationship between the delay in starting adequate antimicrobial therapy and clinical outcome, a role for serial measurements of WCC and especially CRP serum concentrations in the early detection, as well as for follow up of bacteremia among critically ill patients may be presumed." (PMID 17868441, 2007).
bacteremia (continued). "Our findings demonstrated that MDW outperformed traditional inflammatory biomarkers, such as WBC, CRP and NLR, in predicting bacteremia among patients at the ED." (PMID 41598332, 2026). "The combined use of presepsin with CRP and/or PCT improved the predictive capacity for bacteremia, as confirmed by multivariate logistic regression and ROC analysis." (PMID 40647525, 2025). "Presepsin achieved near-perfect accuracy in some cohorts (AUC up to 0.996), outperforming CRP and PCT, though its ability to discriminate bacteremia at fever onset varied." (PMID 40647525, 2025). "We aimed to investigate the performance of human-neutrophil lipocalin (HNL), procalcitonin (PCT), C-reactive protein (CRP), and leucocyte count in conjunction with clinical scores for the early prediction of bacterial sepsis." (PMID 40598497, 2025). "Presepsin showed near-perfect accuracy (AUC = 0.996 at ≥951 pg/mL) for combined bacteremia/clinically proven infections, with significantly higher AUCs than PCT and CRP (p < 0.001)." (PMID 40647525, 2025). "For the prediction of bacterial sepsis, PCT outperformed the other biomarkers with an AUC (95% CI) of 0.77 (0.72–0.82), compared to HNL 0.72 (0.67–0.77), CRP 0.71 (0.66–0.76), and leucocyte count 0.64 (0.59–0.70)." (PMID 40598497, 2025). "Also, our study demonstrated that the presence of bacteremia in the initial blood sample taken from intensive care patients holds significant diagnostic and prognostic value even without waiting for species-level identification when combined with markers such as PCT, CRP, and IL-6." (PMID 41011807, 2025). "For the prediction of bacterial sepsis, PCT outperformed serum HNL (p = 0.049), CRP (p = 0.033) and leucocyte count (p < 0.001)." (PMID 40598497, 2025). "A combination of biomarkers (serum HNL or CRP plus leucocytes) with NEWS and SOFA at presentation outperformed inflammatory biomarkers used individually in the prediction of bacterial sepsis." (PMID 40598497, 2025). "Using a cutoff of >16.6 pg/mL, IL-6 achieved 92.8% sensitivity, outperforming CRP (73.1%) and procalcitonin (PCT; 33.8%) in bacteremia detection (p < 0.01)." (PMID 40647525, 2025). "While more sensitive than CRP (29%), IL-6’s elevation in 57% of FUO episodes (37/65) and failure to detect 26% of bacteremia (9/34) precluded standalone use for antibiotic decisions." (PMID 40647525, 2025). "Conversely, levels of platelet count, CRP, PCT, blood glucose, and triglycerides were significantly higher in the bacteremia group (all p < 0.05)." (PMID 40792110, 2025). "The initial high values in the bacterial sepsis group, which equalized with those in the viral sepsis group over time, were also observed in PCT and CRP." (PMID 40733612, 2025). "The ROC analysis of the study biomarkers for the outcome of bacterial sepsis showed the following AUC (95%CI): serum HNL 0.72 (0.67–0.77), PCT 0.77 (0.72–0.82), CRP 0.71 (0.66–0.76), and leucocyte count 0.64 (0.59–0.70)." (PMID 40598497, 2025). "PCT outperforms C-reactive protein (CRP), absolute neutrophil count (ANC), and white blood cell count (WBC) in the identification of febrile infants with bacteremia and bacterial meningitis." (PMID 38715662, 2024). "In ruling out bacteremia in patients suspected of having a UTI, CRP had an AUROC of 0.689 (95% CI 0.598–0.780) with a 95% sensitivity cut-off of 14 mg/L." (PMID 38542009, 2024). "PCT, CRP, and NLR values were all significantly lower in candidemia compared with bacteremia (0.29 (0.14-0.69) vs. 1.73 (0.5-6.9) ng/mL, p < 0.001, 6.3 (2.4-11.8) vs. 19 (10.7-24.8) mg/dl, p < 0.001 and 6 (3.7-8.6) vs. 9.8 (5.3-16.3), p = 0.001, respectively)." (PMID 38930085, 2024). "The assessment of serum indicators like C-reactive protein (CRP), procalcitonin, and interleukin-6 together has proven effective in accurately detecting bacterial sepsis, aiding in decisions regarding the insertion of epidural catheters." (PMID 39108409, 2024).
bacteremia (continued). "In recent years, medical practitioners have explored more rapid biomarkers for diagnosing bacteremia, including procalcitonin (PCT), C-reactive protein (CRP), and interleukin-6 (IL-6)." (PMID 39885965, 2024). "All cases of bacteremia and meningitis had white blood cell abnormalities (WBC above 15 × 103 or under 5 × 103) and elevated C-reactive protein (CRP > 2.5)." (PMID 37176683, 2023). "With regard to laboratory tests, there is evidence of elevated maternal white blood cell count, increased C-reactive protein (CRP) and, in severe cases, bacteremia." (PMID 37110434, 2023). "The outcomes illustrated that the levels of body temperature, CRP, PCT, IL-6 and IL-8 in bacteremia patients were 38.4°C, 93.7 mg/L, 0.79 ng/mL, 145.00 pg/mL and 34.6 pg/mL, respectively." (PMID 35463642, 2022). "ROC curve analysis for predicting bacteremia yielded an AUC value of 0.685 (95% CI: 0.628–0.741) for presepsin, 0.791 (95% CI: 0.742–0.840) for PCT, and 0.637 (95% CI: 0.572–0.701) for CRP." (PMID 36072944, 2022). "Biomarkers, such as leukocyte count, C-reactive protein (CRP), and procalcitonin (PCT), have been commonly used to predict the occurrence of life-threatening bacteremia and provide prognostic information, given the need for prompt intervention." (PMID 35351003, 2022). "Compared to other biomarkers, including C-reactive protein (CRP) and procalcitonin (PCT), NLR shows good correlation and comparable performance in diagnosing bacterial sepsis in emergency care settings." (PMID 36153405, 2022). "CRP, PCT, PSEP, and BDG serum levels were determined in blood culture-positive patients (candidemia n = 58, bacteremia n = 107)." (PMID 35330311, 2022). "Among the 102 patients with completely normal CRP and PCT levels but high IL-6 levels (≥100 pg/mL), infectious diseases and bacteremia or fungemia occurred in 36 (35.3%) and 9 (8.8%) patients, respectively, until discharge (median HD of 5 days)." (PMID 36555941, 2022). "In contrast, despite its lower power (area under the ROC curve [AUC] = 0.569) to predict bacteremia than PCT (AUC = 0.729), CRP remains an effective yet cheaper and more widely available inflammatory marker for guiding antimicrobial therapy." (PMID 35351003, 2022). "In children with bacteremia, ANC, CRP and PCT levels were higher (median 12,256 vs. 9,251/mm3, 223 vs. 72 mg/L and 8.6 vs. 1.0 ng/mL, respectively; p ≤ 0.002), but WBC levels were not." (PMID 34746044, 2021). "The NPV of the IMS for detection of bacteremia ranges from 96.0–97.0% among the overall population, while the NPV for CRP is 90.0–91.5%." (PMID 33647009, 2021). "In this large, prospective, multicenter study, we aimed at assessing the performance of four biomarkers (WBC, ANC, CRP, and PCT) to predict bacteremia in a population of children with CAP." (PMID 34746044, 2021). "Previous studies have found the levels of the inflammatory markers, C-reactive protein (CRP) and procalcitonin (PCT), to vary between bacteremia and candidemia groups." (PMID 34684298, 2021). "In summary, CRP and PCT are the best routinely available biomarkers to predict bacteremia in children with CAP." (PMID 34746044, 2021). "There are some reports suggesting that C-reactive protein (CRP) and procalcitonin (PCT) can be used to diagnose bacterial sepsis; however, their role and other cytokines in diagnosis of fungal infections has not been clearly demonstrated." (PMID 34684298, 2021). "Several biomarkers [white blood count (WBC), neutrophils, C-reactive protein (CRP) and procalcitonin, among others] have been studied in SCD patients with bacteremia and other bacterial infections with variable results." (PMID 34344349, 2021). "Lymphocytopenia performs better in predicting bacteremia in an emergency care setting than either the WBC count, neutrophil count or CRP level." (PMID 34737270, 2021).